ALKBH5 (alkB homolog 5, RNA demethylase)
Diseases named in the same sentence as ALKBH5 in open-access papers (continued):
Sharing a sentence is not in itself a finding about the gene and the disease.
Sepsis (13 papers, 2020 to 2025). Sepsis is defined as life-threatening organ dysfunction caused by a dysregulated host response to infection. "This study suggests that Alkbh5 plays a significant pathological role in sepsis‐associated ALI by mediating m6A‐dependent Ccl1 mRNA degradation, which aggravates tissue damage and inflammation by reducing Treg recruitment." (PMID 40254698, 2025). "Collectively, ALKBH5 governs neutrophil biogenesis, mobilization, and migration, and its loss severely compromises host antibacterial defense and exacerbates sepsis progression." (PMID 41562066, 2025). "This evidence verified that Alkbh5 mediates RNA degradation of Ccl1 to reduce Treg recruitment to the inflammation site, thus reducing inflammation resolution and aggravating sepsis‐associated ALI." (PMID 40254698, 2025). "In summary, this study reports the critical pathological role of Alkbh5 in inflammatory damage in sepsis‐associated ALI." (PMID 40254698, 2025). "The findings from this study suggest that Alkbh5‐mediated m6A demethylation plays a crucial role in modulating the inflammatory response in sepsis‐associated ALI by affecting Ccl1 mRNA stability and Treg dynamics." (PMID 40254698, 2025). "This study explored the mechanism by which the m6A demethylase ALKBH5 mediates epithelial–mesenchymal transition (EMT) in sepsis‐associated acute kidney injury (SA‐AKI) and AKI‐chronic kidney disease (CKD) transition." (PMID 39287046, 2024). "Consistently, qRT‒PCR showed that the Csf3r mRNA level was indeed decreased in bone marrow neutrophils from Alkbh5-deficient mice compared with those from their WT littermates during sepsis." (PMID 38114747, 2024). "ALKBH5, a m6A erase, was significantly downregulated in sepsis, and ALKBH5 deficiency would suppress the expression of the chemokine receptor CXCR2, which inhibited neutrophil migration and inflammation during bacterial infection." (PMID 37701433, 2023). "During sepsis, Alkbh5-deficient mice exhibited substantially reduced neutrophils in the peritoneal fluid than their WT littermates, suggesting that ALKBH5 is required for protective neutrophil accumulation in the site of infection." (PMID 35764614, 2022). "In a mid-grade sepsis, the in vivo bacterial titer in the peritoneal lavage fluid and blood of Alkbh5-deficient mice markedly increased, especially at the late stage of sepsis." (PMID 35764614, 2022). "This evidence suggests the important pathological role of Alkbh5 in sepsis‐associated ALI." (PMID 40254698, 2025). "Fluorescence-activated cell sorting (FACS) analyses revealed dramatically enhanced release of mature neutrophils from the bone marrow into the peripheral blood in WT mice during sepsis compared with the steady state, yet this increase was far less profound in Alkbh5-deficient mice." (PMID 38114747, 2024). "Interestingly, Alkbh5-deficient mice exhibited a higher percentage of mature neutrophils in the bone marrow during sepsis, suggesting a defect in the egress of neutrophils from the bone marrow to blood in Alkbh5-deficient mice." (PMID 38114747, 2024). "Accordingly, Alkbh5-deficient mice displayed substantially reduced numbers of mature, immature, and total neutrophils in the peritoneal cavity, the infection site, during sepsis." (PMID 38114747, 2024). "RNA-seq analysis showed that Alkbh5 deficiency in neutrophils resulted in up-regulation of 297 genes and down-regulation of 264 genes at the early stage of sepsis, while up-regulation of 197 genes and down-regulation of 337 genes at the late stage of sepsis." (PMID 35764614, 2022). "We performed transcriptome-wide RNA sequencing (RNA-seq) on neutrophils isolated from the peritoneal cavity of Alkbh5-deficient mice and WT littermates during early stage of sepsis (12 h after mild CLP) or late stage of sepsis (36 h after mild CLP), respectively." (PMID 35764614, 2022).
Sepsis (continued). "Notably, ALKBH5 deletion led to significant suppression of Cxcr2 transcripts in neutrophils, which was consistent with our in vivo observation about decreased CXCR2 protein expression on Alkbh5-deficient peritoneal neutrophils during early stage of sepsis." (PMID 35764614, 2022). "The cell-surface expression of CXCR2 protein was significantly decreased on ALKBH5-deficient dHL-60 human neutrophils infected with E.coli, which was consistent with our in vivo results that loss of ALKBH5 declined CXCR2 protein expression on neutrophils from sepsis mice." (PMID 35764614, 2022). "Overall, these results suggest that Alkbh5 exacerbates sepsis‐induced lung injury by destabilising Ccl1 mRNA via m6A demethylation, leading to reduced Treg infiltration." (PMID 40254698, 2025). "We used cecal ligation and puncture (CLP)-induced polymicrobial sepsis to model systemic bacterial infection, and we report that ALKBH5 is required for emergency granulopoiesis and neutrophil mobilization." (PMID 38114747, 2024). "RNA-sequencing analysis of peritoneal neutrophils identified differentially expressed genes in wild-type and Alkbh5-knockout cells from early- (12 h) or late-stage CLP-induced sepsis (36 h)." (PMID 37509095, 2023). "The analysis of the gene expression profiling datasets of a sepsis cohort (GSE5772) revealed that ALKBH5 is expressed at a lower level in neutrophils from peripheral blood of septic patients compared to that from non-septic control patients (left)." (PMID 35764614, 2022). "Conversely, targeting Alkbh5 or supplementing Ccl1 could offer therapeutic benefits in managing sepsis‐induced lung injury." (PMID 40254698, 2025). "More relevantly, in a mouse model of cecal ligation and puncture‐induced polymicrobial sepsis, Alkbh5 was found to play a critical role in emergency granulopoiesis and neutrophil mobilisation to infection sites, key events that contribute to inflammation and tissue damage." (PMID 40254698, 2025). "Moreover, the percentages and absolute counts of immature circulating neutrophils and total circulating neutrophils were markedly decreased in Alkbh5-deficient mice compared with their WT littermates 12 h after CLP, i.e., the early stage of sepsis." (PMID 38114747, 2024). "However, a significant reduction in immature neutrophils in the bone marrow was observed in Alkbh5-deficient mice in the sepsis model beginning 12 h after CLP, the early stage of bacterial infection, indicating that a severe defect in emergency granulopoiesis results from ALKBH5 deletion." (PMID 38114747, 2024). "Therefore, activation or upregulation of the ALKBH5-m6A demethylation axis, an intrinsic mechanism for driving efficient neutrophil migration, may be a potentially promising approach to the treatment of sepsis and other bacterial infectious diseases." (PMID 35764614, 2022). "ALKBH5 attenuated the stability of the mRNA of WNT5A and incited the process of angiogenesis, which exacerbated the hypoxia of CMs during sepsis attacks." (PMID 34869371, 2021). "We observed substantial heterogeneity in the expression of demethylases (ALKBH5, FTO) and methyltransferase complex components (WTAP, METTL3, METTL14), suggesting their potential involvement in the epigenetic regulation of immune function during sepsis." (PMID 40625751, 2025). "Loss of ALKBH5 did not alter the levels of CXCL12 and CXCL5 in the plasma, bone marrow or peritoneal lavage fluid of mice in the steady state or during sepsis." (PMID 38114747, 2024). "Similarly, leukocytes from Critically ill patients with Gram-negative sepsis have a reduced expression of ALKBH5 (right), as showed in another sepsis cohort (GSE6535)." (PMID 35764614, 2022). "In our study, mice lacking ALKBH5 expression exhibited significantly impaired emergency granulopoiesis and neutrophil mobilization beginning 12 h after CLP, i.e., the early stage of sepsis." (PMID 38114747, 2024).
endometrial cancer (12 papers, 2019 to 2025). Primary or metastatic malignant neoplasm involving the endometrium (mucous membrane that lines the endometrial cavity). "Additionally, the high expression of ALKBH5-mediated demethylation was associated with the metastasis and poor prognosis of various female reproductive system tumors, including cervical cancer, endometrial cancer, and ovarian serous carcinoma." (PMID 40001461, 2025). "For instance, in vitro studies have demonstrated that the down-regulation of ALKBH5 can inhibit the growth and invasion of endometrial cancer cells." (PMID 37684273, 2023). "Due to that the regulation of ALKBH5 on endometrial cell activity depended on its demethylation activity, we intended to identify the transcripts with demethylation in endometrial cancer." (PMID 32913456, 2020). "Here, we found that RNA demethylase ALKBH5 expression was significantly upregulated in endometrial cancer, ALKBH5 was then identified to positively regulate proliferation and invasion of endometrial cancer." (PMID 32913456, 2020). "We further confirmed that the protein levels of ALKBH5 were significantly upregulated in endometrial cancer." (PMID 32913456, 2020). "Herein, we found that RNA demethylase ALKBH5 expression was significantly upregulated in endometrial cancer clinical samples." (PMID 32913456, 2020). "Intriguingly, we identified that the mRNA levels of RNA m6A demethylase ALKBH5 were significantly upregulated in endometrial cancer compared to adjacent normal endometrium." (PMID 32913456, 2020). "We find that the RNA demethylase ALKBH5 expression upregulated in endometrial cancer." (PMID 32913456, 2020). "Taken together, these results indicated that upregulation of ALKBH5 may play an important role in the tumorigenesis and progression of endometrial cancer, and led us to further examine how ALKBH5 could regulate endometrial cell activity." (PMID 32913456, 2020). "Together, our results indicate that the m6A demethylase ALKBH5 maybe a potential target to prevent the tumorigenicity of endometrial cancer." (PMID 32913456, 2020). "In endometrial carcinoma, hypoxia and high level of ALKBH5 expression promote the transcription of SOX2 through demethylation, thereby increasing the stem cell-like phenotype of endometrial carcinoma." (PMID 35022030, 2022). "Together, our results may add insights to the m6A demethylase ALKBH5 as an important regulator of the insulin-like signaling pathway in promoting proliferation and invasion of endometrial cancer, providing potential targets to prevent the development of endometrial cancer." (PMID 32913456, 2020). "ALKBH5 promoted the activity of endometrial cell via upregulation of COL1A1 and MMP9 expression, which finally promoted the progression of endometrial cancer." (PMID 32913456, 2020). "Thus, we demonstrated that ALKBH5 promoted proliferation and invasion of endometrial cancer via erasing IGF1R m6A-modifications, which suggests a potential therapeutic target for endometrial cancer." (PMID 32913456, 2020). "ALKBH5 knockdown decreased the expression of key molecular IGF1R and inhibited the activation of insulin-like growth factor signaling pathway and inhibited proliferation and invasion of endometrial cancer in vitro." (PMID 32913456, 2020). "Chen G et.al found that demethylases ALKBH5 could promote pluripotent stem cell transcription factor SOX2 transcription via removing its mRNA methylation, thus sustaining the stemness and tumorigenicity potential of endometrial cancer stem cells." (PMID 37283789, 2023).
myocardial infarction (12 papers, 2021 to 2025). Gross necrosis of the myocardium, as a result of interruption of the blood supply to the area, as in coronary thrombosis. "Early in myocardial infarction, the response of ALKBH5 to hypoxia promotes scar repair and improves cardiac function after infarction." (PMID 39684422, 2024). "ALKBH5 promotes cardiomyocyte proliferation after myocardial infarction while attenuating endothelial cell-mediated post-ischemic angiogenesis." (PMID 38443404, 2024). "After induction of ALKBH5 expression, the myocardial infarction area was significantly reduced, cardiac function was restored, and CM proliferation was promoted after myocardial infarction in young and adult mice." (PMID 37273867, 2023). "Conversely, forced expression of ALKBH5 via adeno-associated virus-9 (AAV9) delivery markedly reduced the infarct size, restored cardiac function and promoted CM proliferation after myocardial infarction in juvenile (7 days old) and adult (8-weeks old) mice." (PMID 33456585, 2021). "It was also reported that m6A methylation was significantly increased and the expression level of ALKBH5 was decreased after birth in the mouse heart and its overexpression promoted myocardial regeneration and repair after the myocardial infarction (MI)." (PMID 35858921, 2022). "The forced expression of ALKBH5 via adenoassociated virus-9 (AAV9) delivery reduces the infarct size, and the cardiac function is restored after myocardial infarction in juvenile (7-days-old) and adult (8-weeks-old) mice." (PMID 36959603, 2023). "Similarly, ALKBH5 suppresses the m6A methylation of MG53 and inhibits MG53 degradation to inhibit cardiomyocyte apoptosis during the myocardial infarction process." (PMID 39519091, 2024). "Therefore, ALKBH5 exerted a protective effect on cardiomyocytes by controlling the stability of various RNAs, potentially reducing the occurrence of cardiac fibrosis following myocardial infarction (MI)." (PMID 39220683, 2024).
rheumatoid arthritis (12 papers, 2020 to 2026). A chronic, systemic autoimmune disorder characterized by inflammation in the synovial membranes and articular surfaces. "For example, FTO, ALKBH5 and YTHDF2 have been described as risk factors for rheumatoid arthritis." (PMID 41009809, 2025). "In the context of rheumatoid arthritis (RA), increased expression of m6A writer proteins and reduced expression of m6A eraser proteins fat mass and obesity -associated protein (FTO) and AlkB homolog 5 (ALKBH5) have been reported to correlate with disease severity." (PMID 41009809, 2025). "Likewise, m6A levels in rheumatoid arthritis (RA) patients’ and ischemic stroke patients’ blood were elevated relative to healthy controls, along with decreased ‘eraser’ ALKBH5 and FTO levels and increased YTHDF2 ‘reader’ levels in RA samples." (PMID 36831575, 2023). "Another report confirmed the involvement of ALKBH5 in the pathogenesis of SLE, as its levels were significantly decreased compared to patients with other diseases (rheumatoid arthritis, hepatitis B virus-infected patients, and tuberculosis patients)." (PMID 33807762, 2021). "For example, global m6A and METTL3 expression levels have been shown to be significantly increased, while FTO, ALKBH5 and YTHDF2 mRNA levels have been shown to be significantly downregulated in rheumatoid arthritis (RA)." (PMID 36457997, 2022). "However, little is known about the role of ALKBH5, FTO, and YTHDF2 in rheumatoid arthritis (RA)." (PMID 32884942, 2020).
Infertility (11 papers, 2021 to 2025). "ATF4 expression was also shown to be substantially elevated during early embryogenesis and testis development, which is consistent with spermatogenesis defects observed in ATF4 null mice and resembling infertility phenotypes observed in ALKBH5-deficient mice." (PMID 39199320, 2024). "Missense mutations in FTO and ALKBH5 have been identified in men who have undergone infertility testing, showing that m6A is related to abnormalities in male sperm and infertility." (PMID 38937660, 2024). "To investigate the cause of infertility in Alkbh5 KO mice, we first analysed testicular development from gross morphology and histological perspectives." (PMID 35368708, 2022). "Similarly, deleting Alkbh5, one of the m6A demethylases, in mouse germ cells also causes infertility due to impaired RNA splicing and apoptosis of spermatocytes." (PMID 38363375, 2024). "Knockout of ALKBH5 has been shown to result in disorder of spermatogenesis and infertility in the male mouse." (PMID 38714941, 2024). "Alkbh5 mRNA is the highest expressed in the mice testes, and the global inactivation of the Alkbh5 gene results in infertile males." (PMID 35652742, 2022). "Generally, m6A modification mediated by ALKBH5 contributes to the development of both spermatocytes and oocytes, suggesting that ALKBH5 may provide novel insights into the potential mechanisms of human infertility." (PMID 40001461, 2025). "ALKBH5 was reported to play an essential role in trophoblast invasion at the maternal–fetal interface, and was proven to be significantly overexpressed in infertile women." (PMID 36555463, 2022). "Simultaneously, several studies indicate that ALKBH5, through regulating the stability of downstream gene mRNA, is involved in the progress of non-tumor diseases, particularly infertility resulting from abnormal reproductive system development." (PMID 38505602, 2024).
pancreatic ductal adenocarcinoma (11 papers, 2020 to 2025). An infiltrating adenocarcinoma that arises from the epithelial cells of the pancreas. "ALKBH5 sensitized pancreatic ductal adenocarcinoma cells to gemcitabine by activating the Wnt pathway." (PMID 36291060, 2022). "In pancreatic ductal adenocarcinoma, silencing ALKBH5 can promote malignant biological behaviors of cancer cells, and also promote the drug resistance of cancer cells to chemotherapy." (PMID 35022030, 2022). "Also, upregulating ALKBH5 expression sensitizes pancreatic ductal adenocarcinoma cells to chemotherapy treatment, indicating that ALKBH5 may play the same role in SCLC." (PMID 34802443, 2021). "In pancreatic ductal adenocarcinoma (PDAC), ALKBH5 works as a tumor suppressive gene, which shows more chemosensitizing to gemcitabine." (PMID 35022030, 2022). "This study analyzed eight m6A regulators (METTL3, METTL14, WTAP, FTO, ALKBH5, and YTHDF1-3) in pancreatic ductal adenocarcinoma (PDAC) and found that only RNA m6A demethylase ALKBH5 serves as an independent favorable prognostic marker for this tumor." (PMID 34733841, 2021). "Interestingly, demethylase ALKBH5 also tend to promote sensitivity to GEM, and decreased ALKBH5 correlates with poor prognosis in pancreatic ductal adenocarcinoma (PDAC)." (PMID 36810281, 2023).